CXCL13 (C-X-C motif chemokine ligand 13)
Diseases named in the same sentence as CXCL13 in open-access papers (continued):
Sharing a sentence is not in itself a finding about the gene and the disease.
optic neuritis (4 papers, 2016 to 2023). Optic neuritis is inflammation of the optic nerve, the nerve that carries the visual signal from the eye to the brain.The conditionmay cause sudden, reduced vision in the affected eye(s). "Of the 21 available samples, 17 (81%) had AH CXCL13 levels of more than 250 pg/mL, with the lowest levels in the patients with optic neuritis." (PMID 38983560, 2022). "Regarding CXCL13, a few studies found that higher CSF levels in CIS patients were associated with the risk of fulfilling McDonald criteria for RMS while one study demonstrated a high risk of conversion to CDMS in patients with optic neuritis." (PMID 36215027, 2023).
oral squamous cell carcinoma (4 papers, 2019 to 2024). "Serum CXCL13 is a potential novel biomarker with diagnostic and prognostic significance for oral squamous cell carcinoma." (PMID 39344390, 2024). "CXCL13 has been also implicated in oral squamous cell carcinoma tumor progression and osteolysis." (PMID 31354634, 2019). "c-Myc activation through the CXCL13:CXCR5 signaling axis stimulates RANKL expression in stromal/preosteoblast cells, therefore implicating CXCL13 as a potential therapeutic target to prevent oral squamous cell carcinoma invasion of bone/osteolysis." (PMID 31354634, 2019). "CXCL13 was shown to significantly enhance the RANKL signaling pathway and osteolysis in oral squamous cell carcinoma (OSCC)." (PMID 36217194, 2022).
osteoarthritis (4 papers, 2021 to 2022). A noninflammatory degenerative joint disease occurring chiefly in older persons, characterized by degeneration of the articular cartilage, hypertrophy of bone at the margins and changes in the synovial membrane. "Our analysis of records from the Gene Expression Omnibus (GEO) database revealed higher levels of CXCL13 expression in RA synovial tissue (n = 10) compared with those in healthy individuals (n = 10) or osteoarthritis (OA) patients (n = 10)." (PMID 34518512, 2021). "Additionally, CXCL13 could induce the proliferation of osteoblasts in osteoarthritis patients." (PMID 36613500, 2022). "The expression levels of TCA1, TLR7, MMP9, CXCL10, CXCL13, HLA-DRA, and ADIPOQSPP1 were significantly higher in the IL-1β-induced group than in the osteoarthritis group in an in vitro qPCR experiment." (PMID 35734177, 2022). "We report significantly higher levels of CXCL13 expression in collagen-induced arthritis (CIA) mice compared with controls and also in synovial fluid from RA patients compared with human osteoarthritis (OA) samples." (PMID 34518512, 2021).
Pneumocystis infection (4 papers, 2010 to 2025). "In Pneumocystis infection, IL‐13 and IL‐17 act synergistically to upregulate Cxcl13 transcription in podoplanin+ stromal cells, implicating both Th2 and Th17 responses in driving iBALT development." (PMID 40815083, 2025). "In addition, as shown in a previous study, Pneumocystis infection can induce both Th2 and Th17 responses, stimulate the secretion of IL-13 and IL-17A, and further facilitate the formation of inducible bronchus associated lymphoid tissue (iBALT) in a Cxcl13-dependent manner." (PMID 37359523, 2023). "During Pneumocystis infection, CXCL13 was required for the formation of inducible bronchus associated lymphoid tissues (iBALT), the ELSs in the lung." (PMID 35309354, 2022). "Among the genes that were affected by dexamethasone and further affected by Pneumocystis infection, Mgst1 and Hspa1b genes were down-regulated, while Cd14, Irf8, Il1b, Cxcl13, Cxcr4, Fn1, Irf1, Cd74, S100a9, and Spp1 genes were up-regulated in all four groups." (PMID 20377877, 2010).
pneumonia (4 papers, 2021 to 2024). An acute, acute and chronic, or chronic inflammation focally or diffusely affecting the lung parenchyma, caused by an infection in one or both of the lungs (by bacteria, viruses, fungi, or mycoplasma.). "Similar to CCL2, in Xue’s study, the serum levels of CXCL13 were significantly lower in the patients with pneumonia and the normal controls than in the IIP group (including IPAF patients)." (PMID 35011819, 2021).
primary biliary cirrhosis (4 papers, 2010 to 2022). "Our group reported before that the levels of serum CXCL13 were significantly higher in primary biliary cirrhosis patients compared to HC." (PMID 28386259, 2017). "It has been demonstrated that the CXCL13 is dense in portal tracts or sinusoids of the liver in hepatitis C virus- infected patients with mixed cryoglobulinemia and in primary biliary cirrhosis." (PMID 26517519, 2015).
pulmonary hypertension (4 papers, 2020 to 2023). Increased pressure within the pulmonary circulation due to lung or heart disorder. "If IPF is associated with pulmonary hypertension or acute exacerbation, serum CXCL-13 will be much higher, which indicates that the situation can be fatal, or the patient needs urgent lung transplantation." (PMID 33101446, 2020). "Of these chemokines and chemokine receptors, Ccl2, Ccl7, Ccl20, Ccl21, Cxcl13, Cxcl4, Ccr6 and Ccr7 have already been demonstrated to be associated with pulmonary hypertension." (PMID 32176619, 2020). "The CXCL13 levels were higher in patients with pulmonary hypertension exacerbations." (PMID 35011819, 2021).
renal carcinoma (4 papers, 2021 to 2025). A carcinoma arising from the epithelium of the renal parenchyma or the renal pelvis. "A high CXCL13 expression in renal cancer patients may indicate the presence of several CD8+-exhausted T cells, suggesting that it can suppress immune function." (PMID 37540227, 2023). "In renal cancer, M2 TAMs are twice as prevalent as in normal tissue, promoting metastasis through midkine (MDK) and chemokines like CXCL13." (PMID 40361374, 2025). "The relationship between CXCL13 expression and the divergent prognostic outcomes of CD8+ T cells in renal cancer patients was further evaluated via correlation analysis." (PMID 37540227, 2023).
squamous cell carcinoma (4 papers, 2020 to 2024). A carcinoma arising from squamous epithelial cells. "For instance, CXCL13 has been found to be overexpressed in various solid tumors, such as squamous cell carcinoma and adenocarcinoma, and has been suggested to play a role in regulating the migration and metastasis of cancer cells." (PMID 37025603, 2023). "Furthermore, our results showed that the expression level of CXCL13 was higher in patients diagnosed with adenocarcinoma compared to those with squamous cell carcinoma." (PMID 37025603, 2023). "The expression level of CXCL13 in adenocarcinoma was higher than that in squamous cell carcinoma." (PMID 37025603, 2023). "Analysis of serum CXCL13 levels in both subtypes of NSCLCs, squamous cell carcinoma (SCC) and adenocarcinoma (AC), showed that serum CXCL13 levels in ACs were higher than that in SCCs; this may be associated with patient prognosis." (PMID 32457792, 2020).
thymoma (4 papers, 2017 to 2024). A neoplasm arising from the epithelial cells of the thymus. "CXCR5 was expressed in B cells, TFH, and CD8 TRM, while its ligand, CXCL13, was expressed in TFH and CD8 TRM, suggesting that the putative role of CXCR5-CXCL13 for T-B interaction in thymoma." (PMID 35869073, 2022). "Another study integrating thymoma tissue and normal thymus transcriptome data identified key transcription factors and signaling pathways such as BCL2 and CXCL13, which may be core mechanisms driving the development of MG thymomas." (PMID 39845831, 2024).
uterine cancer (4 papers, 2021 to 2025). Primary or metastatic malignant neoplasm involving the uterine corpus and/or the cervix. "CXCL13-positive TIL are associated with a high mutation load and, in uterine cancer, B cells were predominantly observed in large aggregations in the tumour and stroma in 92% of POLE samples, compared to 48% of Microsatellite Stable tumours." (PMID 34830795, 2021). "The ‘Genotype’ hypothesis findings for uterine cancer showed that the expression of the genes CMC2, CXCL13, CXCL19, LAG3, SRD5A2, and others had changed." (PMID 40847033, 2025). "Moreover, stimulation with TGFβ induced CXCL13 secretion in CD8+ cells and increased CD103+ CD8+ tumor-infiltrating T cell subpopulation produced CXCL13 in ovarian and uterine cancers." (PMID 36217194, 2022).
abscesses (3 papers, 2019 to 2024). "In addition, CXCL13+ FBs expressed multiple other chemokines (i.e., CXCL12, CCL19), which likely further contribute to the spatial localization of the B cell population at the periphery of actively inflamed abscesses and sinus tracts." (PMID 38051587, 2024).
adult-onset Still disease (3 papers, 2015 to 2019). A rare inflammatory multisystem disorder characterized clinically by fever of unknown origin, arthralgia or arthritis, hyperleucocytosis, and typical skin rash. "When in pathological status of adult-onset Still's disease, the production of CXCL13 was up-regulated, and it was regarded as a crucial chemokine in the establishment of the adaptive immune response in the pathogenesis." (PMID 28018321, 2016).
benign prostatic hyperplasia (3 papers, 2015 to 2023). A non-cancerous nodular enlargement of the prostate gland. "Serum CXCL13 levels are increased in patients with PCa compared to healthy controls and patients with benign prostatic hyperplasia (BPH) or high-grade prostatic intraepithelial neoplasia (HGPIN)." (PMID 37025604, 2023). "The purpose of the current study was to reveal the internal mechanism between CXCL13 and benign prostatic hyperplasia (BPH)." (PMID 36613500, 2022).
chronic hepatitis B (3 papers, 2017 to 2022). "These cases suggest that the increase in the serum levels of CXCL9, CXCL10, CXCL11, and CXCL13 were associated with attaining an HBsAg loss in children with chronic hepatitis B." (PMID 37206604, 2020). "High levels of CXCL13 in patients with chronic hepatitis B stimulated the recruitment of CXCR5+ CD8+ T cells to produce high levels of HBV-specific interferon-γ and IL-21 in patients with chronic HBV infection to improve viral control." (PMID 35844446, 2022). "However, the expression and function of CXCL13 in patients with chronic hepatitis B (CHB) remain unknown." (PMID 28386259, 2017).
Cirrhosis (3 papers, 2019 to 2025). A chronic disorder of the liver in which liver tissue becomes scarred and is partially replaced by regenerative nodules and fibrotic tissue resulting in loss of liver function. "CD8+ T cell subsets exhibited heterogeneity in liver cirrhosis, exhausted T (Tex) cells were increased in cirrhosis, and CXCL13+ Tex cells display an exhausted phenotype associated with immune dysregulation and advanced disease." (PMID 41488615, 2025). "During cirrhosis, there is episodic bacterial translocation and persistent immune cell activation, as indicated by the increased FABP2 and CXCL13 levels in our study." (PMID 31456809, 2019). "Interestingly, the expression levels of CXCL13, TNFSF8, and TNFRSF8 correlated negatively with the expression of retinol binding protein 4 (RBP4), which is decreased in cirrhosis, and positively with the expression of COL1A1, which reflects liver fibrosis." (PMID 40014629, 2025).
Cryptococcal meningitis (3 papers, 2023 to 2025). Meningeal inflammation produced by cryptococcus neoformans, an encapsulated yeast that tends to infect individuals with acquired immunodeficiency syndrome and other immunocompromised states. "The reason for this may be that CXCL13 may be involved in the occurrence of NS, and the mechanism of NS occurrence may be different from cryptococcal meningitis, varicella encephalitis, and other spirochetes that invade the blood-brain barrier." (PMID 41221293, 2025).
gastritis (3 papers, 2015 to 2020). Inflammation of the stomach. "CXCL13 is found in naturally occurring gastric mucosa-associated lymphoid structures that develop in response to chronic Helicobacter pylori infection, and CXCL13-CXCR5 interactions contribute to the development of both H. pylori-associated gastritis and gastric lymphomas." (PMID 28603659, 2016). "CXCL13, also named B-cell-attracting chemokine-1 or B-lymphocyte chemoattractant, is a CXC subtype member of the chemokine superfamily, and it may play a pivotal role in various immune and inflammatory conditions as well as H. pylori-associated gastritis in humans." (PMID 25889172, 2015).
head and neck cancer (3 papers, 2017 to 2025). A primary or metastatic malignant neoplasm affecting the head and neck. "In addition, TCGA data showed that head and neck carcinoma patients with high CXCL13 expression had improved overall survival and progression-free survival than those with low CXCL13 expression." (PMID 40295492, 2025).
idiopathic interstitial pneumonia (3 papers, 2021 to 2024). A class of diffuse lung diseases that typically affect the pulmonary interstitium, although some also have a component affecting the airways (for instance, Cryptogenic organizing pneumonitis). "While combined detection of CCL2, KL-6, and CXCL13 improves diagnostic accuracy for idiopathic interstitial pneumonia (IIP), it does not effectively differentiate among lung fibrosis diseases." (PMID 39850880, 2024).
Immunodeficiency (3 papers, 2022 to 2025). Failure of the immune system to protect the body adequately from infection, due to the absence or insufficiency of some component process or substance. "By the time the study was performed, there was not enough evidence to recommend CXCL13 test as a routine diagnostic tool, and PCR in CSF was recommended in very early LNB with negative IAI, or in patients with immunodeficiency, on the basis of good practice points." (PMID 35889111, 2022).
leprosy (3 papers, 2019 to 2025). Leprosy is a chronic infectious disease affecting primarily the skin and peripheral nervous system. "In leprosy, CXCL13 was associated with lipid metabolism, inflammatory response, and cellular immune response." (PMID 40264781, 2025). "Simultaneously, mIHC revealed that CXCL13 also significantly increased in skin lesions from BT subtype of leprosy." (PMID 40264781, 2025). "We also examined CXCL13 levels in the serum and tissues of patients with LL and borderline tuberculoid (BT) leprosy, which is another subtype of leprosy that presents restrict bacillus growth leading to localized disease." (PMID 40264781, 2025). "Compared with healthy controls, there was a significant increase of serum CXCL13 levels in leprosy patients, especially those with BT leprosy." (PMID 40264781, 2025). "Whilst most of the genes overlap between the two comparisons, some genes discriminate leprosy patients from HHC exclusively (MBP, MSR1, TLR1, CAMTA, CXCL13 and TFGB)." (PMID 31784594, 2019). "When comparing leprosy patients to HHC, 16 genes showed significantly different expression for leprosy patients (increased: FCGR1A, IL6, IL15, LRKK2, MBP, MSR1, PACRGv1, TLR1, TLR4; decreased: CAMTA, CD3E, CTLA4, CXCL13, GATA3, LAG3, TFGB)." (PMID 31784594, 2019). "Importantly, whilst most of these genes were also differently expressed in leprosy patients compared to EC, MBP, MSR1, TLR1, CAMTA, CXCL13 and TFGB were differentially expressed in leprosy patients exclusively when compared to HHC." (PMID 31784594, 2019).
myocarditis (3 papers, 2021 to 2025). Myocarditis is a condition that is characterized by inflammation of the heart muscle (myocardium). "This work highlights CXCL13 as a potential Bb diagnostic marker, as well as host factors such as aberrant B cell activity, mononuclear myocarditis, and gut dysbiosis as potential therapeutic targets." (PMID 40576342, 2025). "It is well known that FMD is characterized by myocarditis in piglets and calves in acute and rapidly progressing cases, and the increased CXCL13 expression in the heart and spleen may contribute to GCs forming or may result in hyperinflammation." (PMID 37047294, 2023). "Most tested patients (six of seven patients) had serum increases in the inflammatory cytokine interleukin (IL)-6 and in the chemokines CXCL9, CXCL10, and CXCL13, and the mass cytometry phenotypes of immune cell populations in the blood also showed correlations with myocardial inflammation." (PMID 34686542, 2021).
nephritis (3 papers, 2020 to 2025). Inflammation of renal tissue. "Tph cells influence the differentiation of other Th cells and B cells by producing CXCL13 and various leukocyte cytokines in different regions, thereby playing an indispensable role in the pathogenic mechanisms of various autoimmune renal diseases and other nephritis." (PMID 39390361, 2024). "And in MRL/lpr mice, CXCL13 was involved in the development of nephritis by promoting the recruitment of CXCR5+ T cells to the kidney." (PMID 41164191, 2025).
neuroblastoma (3 papers, 2011 to 2023). Neuroblastoma (NB) is the most common solid, extracranial childhood tumor. "CXCR5 is also expressed on bone marrow-metastatic neuroblastoma cells, which migrate toward CXCL13 in vitro, suggesting CXCL13/CXCR5 signaling may be involved in neuroblastoma metastasis to bone marrow." (PMID 37025604, 2023). "Furthermore, CXCR5/CXCL13 and CXCR1/CXCL1 interactions may specifically contribute to neuroblastoma bone marrow metastasis in part by facilitating transmigration of neuroblastoma cells through the bone marrow endothelium." (PMID 34831167, 2021).
sarcoma (3 papers, 2017 to 2024). A usually aggressive malignant neoplasm of the soft tissue or bone. "Similarly, we observed lower lymphoid-structures-associated B-cell-specific chemokine CXCL13 in C2-enriched sarcomas cluster." (PMID 35278076, 2022). "T‐cells in the sarcoma microenvironment exhibited elevated levels of cytotoxicity (GZMB, GNLY and KLRD1), exhaustion (HAVCR2, CD38, CD160, CXCL13 and CX3CR1), and inflammation (IL33, PPARG, IL6R and SOCS3), suggesting an activated but exhausted phenotype." (PMID 39658531, 2024). "In our cohorts CXCL13, CD21, CD35, FDCSP and SRGN were the best markers for FDC-sarcoma diagnosis and could discriminate 21/22 FDC sarcomas from other mesenchymal tumors by linear discriminant analysis." (PMID 28145886, 2017).
sleeping sickness (3 papers, 2013 to 2019). "Previous studies have shown that increased levels of CXCL-13 and neopterin could be a good diagnostic marker for sleeping sickness and an indicator of the disease stage; rapid detection tests (RDTs) based on the neopterin concentration in the CSF are under investigation." (PMID 31886231, 2019). "But the accuracy of using neopterin and CXCL-13 as biomarkers for sleeping sickness has been demonstrated previously in larger cohorts, and their links with early inflammatory processes of sleeping sickness have been shown." (PMID 31886231, 2019). "The differences in levels of neopterin and CXCL-13 in patients with sleeping sickness may be explained by their production mechanisms." (PMID 31886231, 2019).
spirochetal infection (3 papers, 2014 to 2023). "It has been proven that CXCL13 determination can provide rapid information regarding central nervous system inflammation in patients with selected spirochetosis." (PMID 32331231, 2020). "However, the positivity of CXCL-13 chemokine in the CSF by a rapid point-of-care assay suggested active spirochetal infection and led to further serologic investigation." (PMID 36979313, 2023).
systemic sclerosis (3 papers, 2019 to 2022). A chronic disorder, possibly autoimmune, marked by excessive production of collagen which results in hardening and thickening of body tissues. "Serum CXCL13 levels in systemic sclerosis patients were abnormally elevated, reflecting that CXCL13 has a role in aberrant activation of the immune system." (PMID 34113405, 2021). "CXCL13 overexpression has been associated with immune activation in chronic conditions such as infection with HIV and systemic sclerosis." (PMID 30846990, 2019).